GBA1 (glucosylceramidase beta 1)
Diseases named in the same sentence as GBA1 in open-access papers (continued):
Sharing a sentence is not in itself a finding about the gene and the disease.
Gaucher disease (continued). "GBA1, p.E365K, p.T408M and p.N409S all have been previously identified via GWAS or similar approaches, with p.E365K and p.T408M being risk factors for PD, and p.N409S being a risk factor for PD with and additional association with Gaucher disease." (PMID 37090536, 2023). "Recessive variants in GBA1 cause Gaucher disease, a prevalent form of lysosome storage disease." (PMID 35857503, 2022). "For instance, in Gaucher disease, due to mutations in the GBA1 gene, encoding lysosomal acid β-glucocerebrosidase (GCase), the expression of mutant GCase in different systems, including patient fibroblasts and fly models, induces ER stress and activation of the UPR." (PMID 36345359, 2022). "Homozygous or compound heterozygous mutations in GBA1 gene are well-known to cause Gaucher disease (GD), a lysosomal storage disorder, whereas heterozygous mutations that in the homozygous state lead to GD have been reported to increase the risk for developing PD." (PMID 34194386, 2021). "Bi-allelic variants in the GBA1 gene are associated with Gaucher disease." (PMID 34497401, 2021). "Indeed, many lysosomal storage disorders display pronounced neurodegeneration and of relevance here, GBA1, the gene that encodes the lysosomal enzyme glucocerebrosidase and is mutated in Gaucher's disease, is a major genetic risk factor for PD." (PMID 33769432, 2021). "Notably, heterozygous mutations in the GBA1 gene encoding glucocerebrosidase, whose homozygous mutations cause Gaucher’s disease, constitute the most common genetic risk factor for idiopathic PD." (PMID 33036336, 2020). "Another lysosomal storage disorder, Gaucher disease, has been found to not only be affected by α-syn aggregates, but mutations in Gaucher's causative gene (GBA1) have been identified as one of the strongest risk factors for developing PD." (PMID 33424556, 2020). "These drugs, which have been shown in different disease models to increase glucocerebrosidase activity, could have potential as a therapy for Gaucher disease and GBA1- associated Parkinson disease." (PMID 32509770, 2020). "Gaucher disease (GD) is an autosomal recessive inborn error of metabolism caused by deficient activity of glucocerebrosidase (GCase) enzyme due to pathogenic mutations in the GBA1 gene (OMIM 606463), located on chromosome 1 (1q21)." (PMID 31931749, 2020). "Related to PD, GBA1 mutations are the most common genetic risk factor for developing PD and GCase activity has been demonstrated to be defective in fibroblasts derived from PD patients harboring the GBA1 mutations or in a mouse model of Gaucher’s disease that presented α-syn accumulation." (PMID 32138193, 2020). "Moreover, a mutation in glucocerebrosidase 1 (GBA1) which causes Gaucher disease has been identified as a potential genetic risk factor for PD, and both Gaucher disease patients and obligate carriers are predisposed to PD." (PMID 32154247, 2020). "Bi-allelic GBA1 mutations cause Gaucher's disease (GD), the most common lysosomal storage disorder." (PMID 31519738, 2019). "Gaucher’s disease is caused by genetic mutations of GBA1, resulting in the loss of GBA1 activity." (PMID 31447678, 2019). "Gaucher Disease (GD) is one of the most common Lysosomal Storage Disorders resulting from deficiency of the lysosomal enzyme glucocerebrosidase, secondary to mutations in the GBA1 gene." (PMID 31488169, 2019). "Gaucher disease is caused by mutations in GBA1 encoding acid β-glucosidase (GCase)." (PMID 30944381, 2019). "Furthermore patients with Gaucher disease with homozygous mutations in GBA1 exhibit an even lower level of GCase activity, although most of them never develop PD." (PMID 31031582, 2019). "Mutations in GBA1 gene lead to Gaucher’s disease, the most prevalent lysosomal storage disorder." (PMID 28835999, 2018).
Gaucher disease (continued). "Glucocerebrosidase (GBA1) gene mutations, encoding gluco-cerebrosidase 1 (GCase 1) which catabolizes glycolipid glucocerebroside to ceramide and glucose in lysosome and responsible for Gaucher disease, are the most common genetic risk factor for PD." (PMID 29719505, 2018). "Homozygotic mutations in the gene coding for GCase (GBA1) cause Gaucher’s disease (GD)." (PMID 28835999, 2018). "Gaucher disease (GD) (Online Mendelian Inheritance in Man ID: 230800) is the most prevalent lysosomal disorder, caused by pathogenic mutations in the GBA1 gene, leading to a deficient activity of the lysosomal enzyme glucocerebrosidase (GCase) (Enzyme Commission 3.2.1.45)." (PMID 28098793, 2017). "GBA1 mutations have been implicated in both Gaucher disease (GD) and Parkinson disease (PD)." (PMID 28295625, 2017). "Furthermore, loss of GBA1 activity down-regulated GBA2 activity in fibroblasts from patients with Gaucher disease." (PMID 29234271, 2017). "Carriers of a single mutant GBA1 allele are unaffected by Gaucher disease." (PMID 27126635, 2016). "One such LSD is Gaucher disease (GD), caused by mutations in the GBA1 gene, which encodes the lysosomal enzyme, acid-β-glucosidase (glucocerebrosidase, GCase), resulting in the accumulation of the sphingolipid glucosylceramide (GlcCer) and its deacylated form, glucosylsphingosine (GlcSph)." (PMID 27175482, 2016). "Thus, insufficient formation of ceramide caused by GBA1 defects was assumed to promote p38 activation and its-driven inflammatory responses in Gaucher’s disease." (PMID 26312487, 2015). "Various other recognized features of Gaucher disease have been documented, predominantly in female Prkca−/− mice, including marrow infiltration, loss of GBA1 expression, splenomegaly, reduced cortical thickness, bone vascular changes, and impaired platelet aggregation." (PMID 25070889, 2014). "Over 350 mutations in GBA1 have been reported worldwide in Gaucher disease patients." (PMID 23520473, 2013). "In addition to visceral processes, some correlations of neuropathologic involvement with gene expression profiles in brains from neuronopathic Gaucher disease patients or Gba1 variant mice provide isolated cross-sectional views of the disease processes." (PMID 21223590, 2011). "We identified 13 additional heterozygous variants in GBA1 (p.R502C, p.A495P, p.L483R, p.D448H, p.E427X, p.G416S, p.N409S, p.R398X, p.R296Q, p.G241R, p.N227S, p.S212X, and p.R159W) that have been reported as disease-causing for Gaucher disease in homozygous state." (PMID 40813364, 2025). "Both subjects, asymptomatic for Gaucher disease, were studied in order to confirm heterozygous compound mutation in the proband and to provide genetic counseling, since heterozygous mutations in the GBA1 gene are considered the main risk factor for the development of Parkinson’s disease." (PMID 40332757, 2025). "Thirteen additional heterozygous variants in GBA1 — p.R502C, p.A495P, p.L483R, p.D448H, p.E427X, p.G416S, p.N409S, p.R398X, p.R296Q, p.G241R, p.N227S, p.S212X, and p.R159W — were identified in our study, and have been reported as disease-causing for Gaucher disease in homozygous state." (PMID 39606324, 2024). "The hypothesis that ambroxol (ABX) could potentially be useful in DLB originated in studies on Gaucher disease (GD), a lysosomal storage disorder, caused by a mutation in the glucocerebrosidase (GCase) gene (GBA1) and resulting in the development of parkinsonism in some patients." (PMID 37304077, 2023). "High levels of glucosylceramides have been associated with sporadic Parkinson’s disease and neurologic forms of Gaucher disease that result from heterozygous or homozygous “loss-of-function” mutations of the GlcCer-degrading enzyme, acidic lysosomal glucocerebrosidase (GBA1)." (PMID 35453664, 2022).
Gaucher disease (continued). "Mutation in the gene (GBA1) encoding for β-glucocerebrosidase (GCase), the lysosomal enzyme responsible for cleaving GluCer into glucose and ceramide, leads to elevated levels of GluCer and is the underlying cause of the most common lysosomal storage disorder known as Gaucher’s disease." (PMID 35782380, 2022). "The exact underlying pathomechanism of p-syn deposition in patients with GBA1 mutations is still unclear, but there is evidence that impaired lysosomal function and endoplasmatic reticulum stress play a role and that accumulation of alpha synuclein is promoted by glucocerebrosidase deficiency." (PMID 30619053, 2018). "Given the critical role of GBA1 in these key pathways for cellular homeostasis, it can be expected that alterations in this enzyme may influence also cancer development and/or pathology, keeping in mind that Gaucher disease is associated with an increased risk of cancer development." (PMID 41857000, 2026). "To assess efficacy, we established a rapidly progressive Gaucher disease mouse model by inducing hematopoietic-specific Gba1 deletion in a D427V background." (PMID 40894035, 2025). "The main goal was to establish which kind of cells would serve as the best possible model to study GBA1, including aspects of Gaucher disease (GD)." (PMID 40141367, 2025). "Gaucher disease, a lysosomal storage disorder (LSD) caused by β-glucocerebrosidase (GBA1) deficiency, is modeled in mice with a complete knockout GBA1−/− or mutations in this gene." (PMID 41155400, 2025). "Our study reinforces the pivotal role of the GBA1 genotype in shaping the clinical spectrum of Gaucher disease, particularly in relation to skeletal and neurological manifestations." (PMID 41155380, 2025). "This study examined GD1 patients from the Spanish Gaucher Disease Registry carrying heterozygous GBA1 genotypes distinct from NM_000157: c.[1226A>G](N370S); [1448T>C](L444P)." (PMID 41155380, 2025). "Diagnosis of Gaucher disease is confirmed through measurement of glucocerebrosidase activity in leukocytes and analysis of the GBA1 gene." (PMID 40218154, 2025). "Gaucher disease (GD) is characterized by significant phenotypic heterogeneity, even among patients with identical GBA1 genotypes, suggesting the role of genetic and/or epigenetic modifiers." (PMID 41282474, 2025). "Gaucher disease (GD) is a rare, autosomal recessive lysosomal storage disease (LSD) caused by pathogenic variants in the glucosylceramidase beta 1 (GBA) gene, located on chromosome 1q21." (PMID 41019578, 2025). "This recruitment was markedly diminished in both the C5aR1-deficient Gba1 9V/- and the C5aR1-deficient CBE-mediated glucocerebrosidase-targeted mouse models of Gaucher disease, emphasizing the role of C5aR1 in this process." (PMID 39596318, 2024). "The right lane comprisesa sample of recombinant GBA1 (Cerezyme) used in the clinical treatmentof Gaucher disease as enzyme replacement therapy." (PMID 39213505, 2024). "Unequal pairing with rearrangement between GBA1 and GBA1LP is a frequent cause leading to the generation of gene–pseudogene rearrangements, many of which are causative variants for Gaucher disease." (PMID 39020124, 2024). "In Gaucher disease (GD), biallelic mutations in GBA1 result in defective lysosomal glucocerebrosidase and the cellular accumulation of glucosylceramide (GlcCer) and its downstream metabolite, glucosylsphingosine (GlcSph)." (PMID 37249220, 2023). "This macrophage phenotype is similar to that described for human Gaucher disease, and like human GBA1 heterozygotes, gba1sa1621 heterozygotes had normal macrophages." (PMID 36745788, 2023).
Gaucher disease (continued). "Among the described diseases, a mutation in a single gene caused mastocytosis, thrombotic thrombocytopenic purpura, Gaucher disease, and paroxysmal nocturnal hemoglobinuria (KIT, ADAMTS13, GBA1, and PIG-A genes, respectively)." (PMID 36766791, 2023). "Autosomal recessive mutations in the glucocerebrosidase gene, Beta-glucocerebrosidase 1 (GBA1), can induce Gaucher’s disease, a lysosomal storage disorder." (PMID 37435045, 2023). "gba1sa1621 homozygotes grew into early adulthood but were smaller in size and had curved spines that were previously reported for other zebrafish gba1 mutants, recapitulating the growth retardation and kyphosis seen in many Gaucher disease patients." (PMID 36745788, 2023). "Gaucher disease(GD), the most common LSD, is caused by recessively inherited mutations in the GBA1 gene encoding the lysosomal enzyme, glucocerebrosidase." (PMID 34401403, 2021). "Especially, GBA1 is well-known as a responsible gene for Gaucher disease, the most common lysosomal storage disorder." (PMID 34194386, 2021). "A number of GBA1 mouse models have been developed and described in the published literature for the lysosomal storage disorder Gaucher’s disease (GD)." (PMID 34106956, 2021). "Generally, GCase deficiency is associated with higher intracellular aSyn levels, in neuronal models and iPSC-derived DAergic neurons from Gaucher’s disease and GBA1-PD patients." (PMID 33381501, 2020). "Gaucher disease (GD) (OMIM #230800, #230900 and #231000) is an autosomal recessive disorder most frequently caused by biallelic pathogenic variants in the GBA1 gene that codes for glucocerebrosidase (GCase)." (PMID 32099816, 2020). "Mutations in GBA1, the gene encoding the lysosomal glucocerebrosidase, cause a common form of LSD called Gaucher disease." (PMID 32708198, 2020). "Both heterozygous and homozygous mutant models have been used to emulate GBA1 carriers and patients with Gaucher disease, respectively." (PMID 31464647, 2019). "Gaucher disease (GD) results from mutations in the GBA1 gene, which encodes lysosomal glucocerebrosidase (GCase)." (PMID 31505865, 2019). "There are now many examples of iPSC models to probe neurodegenerative diseases including Gaucher disease Parkinson disease and Parkinson disease with GBA1 heterozygosity." (PMID 31464647, 2019). "Brain sections from a mouse model of the neuronopathic Gaucher disease, known to display a consistent and acute inflammatory response, were used as a positive control (Gba1−/−)." (PMID 29878115, 2018). "A deficit in canonical Wnt pathway was also associated to impaired osteoblast differentiation and reduced bone mineralization in the Gba1 zebrafish model (Gaucher Disease model)." (PMID 28513549, 2017). "Aside from the release of β-GlcCer from cellular damage, this glycosphingolipid is important as it accumulates in Gaucher’s disease, an inherited genetic defect in β-glucosylceramidase (GBA1) that is characterized by systemic inflammation." (PMID 29230225, 2017). "Gaucher disease, a relatively frequent LSD caused by deficiency of lysosomal glucocerebrosidase (Gba), a GBA1 encoded enzyme that degrades glucocerebroside into glucose and ceramide, has already been evaluated under the ncRNA perspective." (PMID 27708618, 2016). "In fact, previous studies showed that GBA1 knockdown potentiates p38-dependent formation of IL-6 in human cell lines, and IL-6 has been shown to increase in serum of patients with Gaucher’s disease." (PMID 26312487, 2015). "Gaucher disease (GD), the LSD with the highest prevalence, is caused by mutations in the GBA1 gene that results in defective and insufficient activity of the enzyme β-glucocerebrosidase (GCase)." (PMID 26045184, 2015). "Some of our findings are remarkably similar to observations in a GBA1 nonsense medaka (Oryzias latipes) model of Gaucher disease." (PMID 26376862, 2015).
Gaucher disease (continued). "Female Prkca−/− mice develop splenomegaly and reduced marrow GBA1 expression reminiscent of Gaucher disease, in which PKC involvement has been suggested previously." (PMID 25070889, 2014). "Previously, viable Gba1 mutant mice were generated to study the pathophysiologic mechanism in Gaucher disease and therapeutic approaches." (PMID 25551612, 2014). "In this study, a mouse model carrying a functional GCS transgene was generated to modulate GlcCer concentration in vivo and to evaluate tissue substrate threshold in Gaucher disease mouse models, Gba1 mutant mice." (PMID 25551612, 2014). "We examined the potential role of GBA2 as a modifier of Gaucher disease and the crosstalk between GBA1 and GBA2 using three subsequent steps." (PMID 24070122, 2013). "The existing literature on this topic is sparse; most reports addressing LRRK2 are limited in scope, while studies of GBA1 have largely concentrated on patients with Gaucher disease rather than PD cohorts carrying heterozygous pathogenic variants." (PMID 41300754, 2025). "HMDMs appear to be the most suitable model for investigations into GBA1 and Gaucher disease." (PMID 40141367, 2025). "Gaucher disease (GD), an autosomal recessive disorder caused by a deficiency in the lysosomal enzyme glucocerebrosidase (GBA) encoded by GBA1 gene, is the most common glycolipid storage disorder, with an overall incidence of approximately 1 in 40,000 to 60,000." (PMID 40515481, 2025). "Moreover, they serve as a valuable model for mannose-receptor mediated uptake of therapeutic human GBA1, effectively mimicking enzyme replacement therapy for Gaucher disease." (PMID 40141367, 2025). "There is a range of PD-risk variants in GBA1, some, but not all, of which are also associated with Gaucher disease; these variants confer varied risk for PD." (PMID 40834859, 2025). "We compared olfactory and motor functions in 119 participants: Sidransky syndrome (n = 18), iPD (n = 30), GBA1 variant carriers without PD (n = 21), Gaucher disease patients (n = 20), and healthy controls (n = 30)." (PMID 40508068, 2025). "For example, ambroxol is a mucolytic drug mainly used for respiratory diseases identified as a candidate PC for treating Gaucher disease (GD), the most common LSD, characterized by a deficiency in lysosomal acid glucosylceramidase (GBA1), leading to organ damage, bone pain, and anemia." (PMID 38540351, 2024). "In this study, we analyzed GBA1 in a large number of Japanese MSA cases using both Sanger and short-read whole-genome sequence analyses to investigate the potential association of variants pathogenic for Gaucher disease with MSA." (PMID 39020124, 2024). "Gaucher disease (GD) is the most common LSD and is caused by mutations in the lysosomal glucocerebrosidase gene GBA1, resulting in the deficiency of enzyme activity; lysosomal glucocerebrosidase normally hydrolyzes the glucose moiety from glucosylceramide (GlcCer) in lysosomes." (PMID 38072450, 2024). "GBA1 N409S significantly reduces GCase activity and causes generally mild and non-neuronopathic Gaucher disease and a mild clinical phenotype in PD27,28." (PMID 36854767, 2023). "It is possible that the lack of association of the severe Gaucher disease GBA1 variants to urinary BMP levels was due to the small numbers of individuals with L483P (N = 10) and the group of rare point/frame-shift mutations (N = 11)." (PMID 36854767, 2023). "Bi-allelic mutations in GBA1, the gene that encodes β-glucocerebrosidase (GCase), cause Gaucher disease (GD), whereas mono-allelic mutations do not cause overt pathology." (PMID 36752535, 2023). "For a few GBA1 variants, some quite commonly carried, such as the E326K variant, this is not the case: Gaucher disease is not caused by carrying biallelic GBA1 variants, even though the variant is thought to be associated with PD23." (PMID 36446806, 2022).